IL4 (interleukin 4)
Diseases named in the same sentence as IL4 in open-access papers (continued):
Sharing a sentence is not in itself a finding about the gene and the disease.
tumor (continued). "This is compatible with the current study, since the maintenance or increment in IL-4 serum concentrations could be driven by the polarization of the microenvironment, skewing the action of the immune system towards a pro-tumor microenvironment, which would be restored after targeted therapy." (PMID 36248816, 2022). "On the other hand, the M2 phenotype secretes cytokines such as IL-4, IL-13, IL-10, vitamin D3, and glucocorticoids, which leads to weakening of the antitumor activity and an enhancement of the ability to support angiogenesis and tissue remodeling, which is beneficial for tumor growth and invasion." (PMID 36611344, 2022). "Since CD4+ Th2 cells and Th2 cytokines such as interleukin-4 (IL-4), IL-5, IL-6, IL10 and IL13 were thought to be associated with immunosuppressive contexture and tumor-promoting effects, we believed that LMNB1 could be considered as a biomarker of immunosuppressive microenvironment." (PMID 35241075, 2022). "Finally, manganese appeared to be a general immunostimulant in our study (higher IL-4, IL-12, TNFα), consistent with the effects of chronic manganese exposure on increased inflammatory, humoral, and anti-tumor activity in murine models and increased IL-1ß in pregnant women." (PMID 36429656, 2022). "Thus, IL4 seems to have a prominent function in the regulation of steroid synthesis, which may contribute to reduced immune suppression in the tumor microenvironment, thereby facilitating tumor growth and metastasis." (PMID 36362361, 2022). "Additionally, anti-inflammatory IL-4 was significantly lower in the tumors of Clic4 KO hosts at 28 days, suggesting net increases in the inflammatory milieu upon CLIC4 loss in the tumor microenvironment." (PMID 35727842, 2022). "Due to the profound potency in terms of the inflammatory activator and cell energy alteration of LPS when compared with IL-4 and tumor supernatant, the limited Dectin-1 upregulation in WGP-activated M1 might be because of the lack of cell energy after LPS stimulation." (PMID 36142859, 2022). "However, secretion and proteolytic release of certain cytokines and growth factors, such as colony stimulating factor-1 (CSF-1) and interleukin-4 (IL-4), by the tumor cells educate TAMs toward a tumor-promoting phenotype, sharing many features of alternatively activated M2 macrophages." (PMID 35998057, 2022). "M2 macrophage behaviour exists more heterogeneously and can be triggered by IL-4 or IL-13, IL1-β, TGF-β, IL-6, phagocytosis of apoptotic cells, or association with a tumour microenvironment, respectively, generating M2a, M2b, M2c, M2f, and tumour-associated macrophages (TAM)." (PMID 36254592, 2022). "IL4 may promote tumor growth and dysregulate antitumor immune responses." (PMID 36362361, 2022). "Interleukin-4 could also promote tumor proliferation and aggressiveness." (PMID 36138874, 2022). "GHCer could be transferred from cancer cells into non-tumor cells located in tumor microenvironment, such as endothelial cells, promoting angiogenesis, as well as into T cells, inhibiting IL-2, interferon-γ, and IL-4 secretion, promoting immunosuppression." (PMID 35158915, 2022). "Moreover, it was reported that IL-4 and IL-10 have a direct anti-proliferative effect on some tumor cells including breast carcinomas,which may be because of their ability to increase the host antitumor response." (PMID 35974992, 2022). "Therefore, we asked whether BM, spleen, and tumor-derived M-MDSCs could differentiate into DCs under standard conditions (GM-CSF + IL-4) and whether the presence of TES would alter the ability of M-MDSCs to become DCs." (PMID 36480485, 2022). "Collectively, these studies suggest that IL-25-mediated activation of ILC2s, and IL-33-mediated stimulation of Th2 cells, may act as independent parallel pathways to induce the production of IL-4 and IL-13 leading to the activation of MDSCs to suppress anti-tumour T cells and promote CRC." (PMID 36263033, 2022).
tumor (continued). "Interestingly, TAMs can acquire different functional phenotypes depending on TME signals; they are capable of having either the classical anti-tumor M1 type in response to IFN-γ or lipopolysaccharide or the alternative pro-tumor M2 type by IL-4, IL-10, IL-13, TGF-β and lactic acid." (PMID 33129234, 2021). "Moreover, Th2 immune responses induced IL-4 and eosinophil-dependent anti-tumor activity." (PMID 35008550, 2021). "In the present study, HNSCC tumor-infiltrating lymphocytes (TILs), which secrete typical cytokines associated with Th1-, Th2-, Th9-, Th17-, and Th21-polarized inflammation (including IFN-γ, IL-4, IL-9, IL-17, and IL-21), were identified using flow cytometric analysis." (PMID 34026621, 2021). "Considering the mostly cancer-promoting effect of tumor-associated macrophages (TAMs), which have a “tumor-friendly”, M2-like phenotype, inhibitors of PARP-14 may have the potential to reverse M2 polarization of TAM, similar to models of IL-4-induced M2 polarization." (PMID 33923319, 2021). "In this study, we hypothesized that the HMC3 cells, upon stimulation with anti-inflammatory cytokines (IL-4, IL-13, IL-10, TGFβ, CCL2) released from cancer cells, will show an increased expression of immuno-suppressive and tumor-supportive proteins and associated pathways." (PMID 34566949, 2021). "Additionally, thioA skewed in vitro differentiated human monocyte-derived macrophages (HMDMs) polarized to M2- or TAM-like phenotypes through incubation with interleukin-4/13 (IL-4/IL-13) or a tumor-conditioned medium, respectively, to a more antitumoral profile." (PMID 34201298, 2021). "Mechanistically, the transcriptional activities of STAT6 downstream of IL-4, and of the peroxisome proliferator-activated receptor Gamma (PPARγ) in conjunction with its co-activator PPARγ-coactivator-1beta (PGC-1β), are key for the differentiation and activation of tumor-associated myeloid cells." (PMID 34831183, 2021). "Hence, the inclusion of fusion receptors such as interleukin (IL)‐4–IL‐7 chimeric cytokine receptors has the propensity to shift the inhibitory signals from IL‐4 to IL‐7 signalling – leading to proliferation and memory differentiation of T cells at the tumor site." (PMID 34188916, 2021). "Furthermore, our results support the idea that the Th2 dominance observed in the tumor stage could be a consequence of the expansion of the malignant TOX+ IL-4+ T cells already present in early-stage lesions." (PMID 34220814, 2021). "Similarly, another study found that the administration of a GRP94 and Her2/neu DNA vaccine to HER2+ breast cancer-bearing mice led to an increased immune response against the tumors evidenced by increased IFN-γ/IL-4 levels and decreased Tregs at the tumor site." (PMID 33898309, 2021). "So IL-4 may have distinct functions, pro- and antitumor, depending on the tumor environment." (PMID 35008550, 2021). "Thus, it should be investigated whether M2-like TAMs induced by IL-4 released from tumor cells enhance tumor radioresistance." (PMID 33959512, 2021). "IL-4-supplemented culture media could increase the tumor-killing abilities of CAR T-cells." (PMID 33855089, 2021). "Some of these cells secrete chemokines (e.g., CCL2/MCP-1), cytokines (e.g., IL-4, IL-13) and growth factors (e.g., VEGF, CSF1/M-CSF and CSF2/GM-CSF) that trigger the recruitment of monocytes, and can promote cancer progression through the activation of tumor-associated macrophages (TAMs)." (PMID 33710603, 2021). "Besides that, tumor-associated macrophages (TAM) can be polarized upon IFN-γ stimulation into a M1 phenotype, which exhibits enhanced anti-tumorigenic properties, or into a M2 phenotype upon IL-4 stimulation, which exhibits pro-tumorigenic activities." (PMID 33946188, 2021). "Interestingly, however, only in GC the correlation resulted from IL-4 accumulation in tumor." (PMID 32512917, 2020).
tumor (continued). "IL-4 secretion regulated by the upstream miR-195/NOTCH axis was confirmed to promote rapid tumour growth through activating recruitment and polarization of the M2-like tumour-associated macrophages, which had long been considered as a risk factor for CRC progression." (PMID 32760201, 2020). "On the other hand, several in vitro and in vivo studies showed, for several types of cancer such as colon, thyroid, breast and lung, that tumor growth could be stimulated by IL-4 through an autocrine loop, inhibition of apoptosis and resistance to death receptors." (PMID 33312693, 2020). "Interestingly, positive correlation between tumor grade and fold-change in IL-4 protein concentration in ESCC patients resulted from a negative correlation observed in adjacent non-cancerous tissue (ρ = −0.60, p = 0.009) and not from an increasing IL-4 accumulation in tumor." (PMID 32512917, 2020). "In supernatants derived from RANK+/+ tumor acini, many cytokines were upregulated including stromal cell-derived factor-1α, macrophage inflammatory protein-1α, interleukin (IL)-1α, stem cell factor, tumor necrosis factor-α, IL-13, macrophage colony-stimulating factor, IL-10, IL-4, IL-17, and IL-1β." (PMID 33303745, 2020). "Indeed, it has been found that targeting the elevated IL-4 in the TME also alters inflammation in the tumor microenvironment, reducing the generation of immunosuppressive M2 macrophages and myeloid-derived suppressor cells (MDSCs), which enhances anti-tumor immunity and delays tumor progression." (PMID 33224886, 2020). "IL4 treatment could contribute to stimulate the immune system against tumour cells." (PMID 32103619, 2020). "Thus, tumor cells can induce M2-type differentiation of macrophages by secreting IL-4 and IL-10." (PMID 33224886, 2020). "Consequently, both tumor promoting and protective roles have been advocated for IL-4 and IL-13." (PMID 32512917, 2020). "Moreover, tumor-derived CSF-1 and IL-4 synergistically induce M2-type polarization of macrophages." (PMID 33224886, 2020). "Cytotoxic T-cell functions are inhibited by cytokines such as IL-4, IL-10 and transforming growth factor (TGF)-β, which are secreted by suppressive immune cells in the TME such as regulatory T (Treg) cells, myeloid-derived suppressor cells, and tumor-associated macrophages/neutrophils." (PMID 32843053, 2020). "However, the role of IL-4 in tumor growth under the condition of STAT6 inactivation is unclear." (PMID 31798581, 2019). "To study whether this was linked to IL-27-signaling in macrophages, we generated BMDM from WT and IL27Rα KO mice and induced classical activation with LPS/IFNγ, alternative activation with IL-4, or directly co-cultured them with PyMT cells to induce tumor-like conditions." (PMID 31637217, 2019). "In an IL-4-dependent manner Stat6 has been suggested to promote colorectal cancer due to its ability to polarize myeloid cells in a wound–healing/tumor-promoting alternative phenotype, which differentiates these cells from the tumor-suppressing IFNγ-mediated classical activation phenotype." (PMID 30353167, 2019). "Mast cells may promote inflammation, inhibition of tumor cell growth, and tumor cell apoptosis by releasing cytokines, such as IL-1, IL-4, IL-6, IL-8, monocyte chemotactic protein-3 and -4 (MCP-3 and MCP-4), transforming growth factor beta (TGF-β), and chymase." (PMID 30678047, 2019). "Hence, upon IL4 engagement, our 4/7ICR delivers a prototypic Th1 cytokine signal (signal 3) that supports cell proliferation, persistence and potent anti-tumor effects, as was confirmed in our primary and rechallenge in vivo tumor models." (PMID 29747685, 2018). "Novel cancer treatments based on IL-10 and IL-4 antibodies could pave the way for tumor elimination despite a worst-case scenario at the start of treatment consisting of a highly immunosuppressive, angiogenic and polarized tumor microenvironment." (PMID 35847834, 2018).
tumor (continued). "On day 21, granulocyte-colony stimulating factor (G-CSF), granulocyte-macrophage (GM)-CSF, IL-4, IL-6, and IL-10 were found to be increased by calcitriol and its analogs, whereas on day 33, their level was found to be decreased as compared with control tumor-bearing mice." (PMID 30037009, 2018). "Thus, IL‐4, similar to other cytokines may be a regulator of tumor‐initiation and hence, may present a suitable therapy target in combination with current treatment options." (PMID 29236307, 2018). "To test whether these lipids in tumor microenvironment would promote the conversion of DCs into metabolically inactive DCs, we generated DCs in vitro from bone marrow by using granulocyte-macrophage colony–stimulating factor and interleukin-4." (PMID 30619288, 2018). "Since Chi3l1 deficiency reduced IL-4 production in Th2 cells while increasing IFNγ expression in Th1 and CD8 T cells, targeting Chi3l1 could provide prominent anti-tumor effect by driving Th1 response while suppressing the activity of tumor-promoting Th2 cells." (PMID 29403003, 2018). "Alternatively, IL-4 and IL-13 produced by Th2 cells induce macrophage polarization towards the M2 phenotype; M2 macrophages secretes anti-inflammatory cytokines such as IL-10, immunosuppressive factors, and tumor growth factors, which promote tumor cell growth and metastasis." (PMID 29707119, 2018). "However, IL-10 and IL-4 are also responsible for pro-tumor cell polarization." (PMID 35847834, 2018). "Interleukin (IL)-4 polarization, referred to as either alternative or M2a activation, promotes a response characteristic of wound healing and parasite immunity, whereas interferon-r polarization, known as classical or M1 activation, programs monocytes for intracellular killing and tumour resistance." (PMID 29614988, 2018). "The complex and versatile interaction between type M2 TAMs and tumor cells could explain an increased production of IL-4, of induced type and not linked to genetic susceptibility, from the tumor microenvironment." (PMID 30526523, 2018). "Interestingly, a significant increase in the serum concentrations of TNF and IL-6 was found in the P2Et/P2Et groups compared with the other groups in both tumor models, while in the P2Et/P2Et-treated B16 tumors, the serum concentrations of both IL-17 and IL-4 were significantly decreased." (PMID 30234017, 2018). "Additionally drugs such as carboplatin, but not other chemotherapies, have been shown to downregulate the programmed death ligand 2 (PDL-2) on both dendritic cells and tumour cells, resulting in enhanced antigen specific T-cell activation, through the IL-4/STAT6 pathway." (PMID 29373959, 2018). "Because the age-dependent high levels of IL-10, IL-4 and IL-5 were subsequently decreased by tumor induction only in multiparous mice in the present model, we suggest that parity during fertile life might improve antitumor immunity in aged mouse challenged with tumor-inducing cells." (PMID 28966800, 2017). "Next, we discuss IL-4 and IL-15 involvement in the generation of innate CD8(+) T cells and particularly its possible dependency on the promyelocytic leukemia zinc-finger factor expressing iNKT cells, an innate T cell subset well documented for its susceptibility to tumor immune subversion." (PMID 28396661, 2017). "However, the binding of TNFSF15 to its receptor, TNFRSF25, amplifies the expression of IL-4, IL-6, GM-CSF, and IL-1758,59, which may explain the overactivity of these tumour-promoting cytokines in our network." (PMID 29062084, 2017). "Moreover, Th2 cells' interaction with the TME and particularly with MSCs inhibits immune rejection of the tumor (through the production of Interleukin-4, IL-4, Interleukin-5, IL-5, and Interleukin-13, IL-13) and promotes the presence of immunosuppressive type 2 macrophages." (PMID 28473858, 2017).
tumor (continued). "Interestingly, blocking IL-4 suppressed BCSCs proliferation, colony forming efficiency and in vivo tumor formation, while it supported the expression of the dual specificity phosphatase-4 (DUSP4) in triple-negative basal-like BCSCs, leading to aggressiveness reduction." (PMID 28927416, 2017). "Moreover, IL-4 interferes with the apoptotic program activated by anticancer agents in tumor cells." (PMID 28609459, 2017). "The other selected IL-4-enhanced miRNA, mir-342-3p, is associated with pro-apoptotic and anti-proliferative functions in different tumor types; it may, therefore, be a potential negative feedback regulator of IL-4-induced macrophage proliferation." (PMID 27245778, 2016). "This is specific to IL-13 as mice lacking IL-4 were significantly less susceptible to tumour development following DMBA–TPA, suggesting that IL-4 may drive inflammation in this model, whereas IL-13 works differently." (PMID 27357235, 2016). "However, in CRC IL-4 rather appears to drive tumor development." (PMID 27148488, 2016). "Furthermore, in vitro coculture of IL-4-secreting CRC-derived tumor-initiating cells with peripheral blood mononuclear cells (PBMCs) was found to inhibit the proliferation of these PBMCs, which could be restored upon addition of IL-4 blocking antibodies." (PMID 27148488, 2016). "Our study presents a conceptual advance in our understanding of the modification of tumor microenvironment by radiation and suggests that combining radiotherapy with genetic therapy to inhibit IL-4 may be a promising strategy for preventing post-radiation recurrence and metastasis in patients." (PMID 27895317, 2016). "Thus, through its effects on multiple cell types and by binding to alternative cell surface receptors, IL-4 plays critical roles in allergic inflammation, immune response to extracellular parasites including helminths, autoimmunity and tumor inflammation and metastasis." (PMID 27214384, 2016). "In addition, morphine prevented IL-4-induced increase in MMP-9 production, indicating that opioids may prevent IL-4-expressing Th2 lymphocytes from promoting macrophage activation in the tumour microenvironment." (PMID 26078009, 2015). "Thus it is possible that higher IL4 production might result in the escape of tumour cells from immune surveillance due to diminished cell mediated immune response." (PMID 26383107, 2015). "However, other studies have shown that malignant tumor cells genetically engineered to produce IL-4 displayed potent anti-tumor effects in vivo, suggesting the potential use of IL-4 secreting tumor cells as tumor vaccines for treating patients with advanced cancers." (PMID 27563494, 2015). "An alternatively activated macrophage phenotype is elicited by interleukin-4 (IL-4), IL-10, or transforming growth factor ß (TGFß), which are produced by helper 2 or regulatory T cells, tumor cells, or macrophages themselves during late stage immune responses and tumor cells." (PMID 26146544, 2015). "However, IL-4 promotes IL-10 in tumor tissue and the latter interferes with the expression of inflammatory factors, including IL-12 and IFN-γ, blocks the activation of NK cells and reduces the antigen formation of tumor cells in order to escape cytoimmunity against tumor growth." (PMID 24520300, 2014). "We determined a clear antitumor effect of IL-12 plasmid DNA against an experimental murine tumor, which was associated with shift to a Th1-type cytokines profile, with expression of IL-2, IL-12 and IFN-γ cytokines and reduced expression of IL-10, IL-4 and TGF-β1 cytokines." (PMID 24808638, 2014). "However, after the tumor was treated with three intratumoral injections of plasmid containing IL-12 cDNA, it showed a cytokine profile associated with Th1 with expression of IL-2, IL-12, and IFN-γ cytokines and reduced expression of IL-10, IL-4, and TGF-β1." (PMID 24808638, 2014).